CCNB1 (cyclin B1)
Diseases named in the same sentence as CCNB1 in open-access papers (continued):
Sharing a sentence is not in itself a finding about the gene and the disease.
breast carcinoma (continued). "Recent research suggested that APS may inhibit the proliferation of MCF-7 breast cancer cells through regulation of control protein 6 homolog (CDC6) and mitotic specific cyclin-B1 (CCNB1)." (PMID 32265719, 2020). "Our study utilized TCGA disease data and molecular target data through network pharmacology to demonstrate that Astragalus polysaccharide intervention in breast cancer may occur through regulation of CDC6 and CCNB1." (PMID 31157164, 2019). "The first intron of the human cyclin B1 gene harbors an NF-κB binding site, as evidenced by the finding that MnSOD-mediated downregulation of NF-κB negatively regulates cyclin B1 expression in MCF-7 breast cancer cells." (PMID 30260967, 2018). "In addition, we treated MDA-MB-436 breast cancer cells with M-FOXM1 Apt and measured the levels of FOXM1, Cdc25B, and Cyclin B1." (PMID 28358012, 2017). "In breast cancer cytoplasmic expression of cyclin B1 protein was recognized in the nonmitotic phase, and nuclear expression in the mitotic phase." (PMID 23722120, 2013). "Cyclin B1 regulates onset of mitosis, and high levels of cyclin B1 in breast cancers has in several studies been shown to be a negative prognostic marker." (PMID 24324728, 2013). "We have here demonstrated the usefulness of GOBO using CCNB1 and the CSR gene signature as two examples for rapid online extraction of gene expression patterns, co-expressed genes, and survival analysis in a large breast cancer data set." (PMID 21445301, 2011). "Similarly, ATO increased cyclin B1 in NB4 APL and MCF-7 breast cancer cells but decreased cyclin B1 in PCI-1 head and neck cancer cells during G2/M arrest induction." (PMID 19897545, 2011). "CCNB1 mRNA expression has been reported to be significantly and positively correlated with mRNA expression levels of CENPE, AURKB, PLK1, and PLK4 in both breast tumors and breast cancer cell lines." (PMID 21445301, 2011). "On that account, specific targeting of oncogene(s) in individual cancer cell lines, like Her-2/neu in SK-BR-3 and BT-474 cells, or cyclin B1 in MCF-7, could improve breast cancer therapy." (PMID 19113992, 2008). "The promoter of cyclin B1 is also upregulated by 17beta-estradiol (E2), insulin-like growth factor I (IGF-I) and prolactin-releasing hormone (PRL), which are considered as the factors contributing to mammary cancer development and progression." (PMID 19113992, 2008). "Ninety genes belonging to the GO category of 'apoptosis', including members of the BAG family (BAG1, BAG2, BAG3), as well as members of the breast cancer 'proliferation signatures' (BUB1, PLK1, CCNE1, CCND1 and CCNB1) were also identified as up-regulated in our DTET." (PMID 17014703, 2006). "Furthermore, heightened levels of CCNB1 have been detected in different types of cancers like HCC, breast cancer, and bladder cancer, suggesting that elevated glucose levels could induce comparable growth signals in trophoblast cells." (PMID 39822992, 2025). "In addition, deletion in the gene for CDKN2A (Cyclin-Dependent Kinase Inhibitor 2A), capable of inducing cell cycle arrest in the G2 phase and apoptosis by preventing the activation of cyclin B1/CDC2 complexes, and acting as a tumor suppressor in breast cancer, is common in HBCX-17 and T174 cells." (PMID 38786044, 2024). "Moreover, the identification of inhibitors that targeting CCNB1 and PLK1 might provide a new idea for treating breast cancer." (PMID 35456460, 2022). "Moreover, CCNB1 and PLK1 are highly expressed in all breast cancer stages, suggesting that they could be further studied as potential drug targets." (PMID 35456460, 2022).
breast carcinoma (continued). "Together, these results suggested that treatment with NTX, PRO, and NTX + PRO downregulated the expression of cyclin B1, CDK1, and the phosphorylation of CDK1, which caused G2/M phase cell cycle arrest without displaying sub-G1 populations in all the breast cancer cells." (PMID 34638341, 2021). "Moreover, six hub genes were selected and validated in clinical sample for further analysis owing to the high degree of connectivity, including CDK1, CCNA2, TOP2A, CCNB1, KIF11, and MELK, and they were all correlated to worse overall survival (OS) in breast cancer." (PMID 31428132, 2019). "However, Chae reported that the expression of cyclin B1 had no influence on the survival of patients with breast cancer." (PMID 22682366, 2012). "Moreover, primary breast cancers harbouring CCNE1 amplification were found to have higher levels of CDK2 mRNA expression, adjusted for proliferation using the mRNA levels of CCNB1, than breast cancers devoid of CCNE1 amplification (P = 0.02789, t-test, data not shown)." (PMID 22433433, 2012). "In addition, consistently up or down-regulated HSP90 client transcripts following treatment were identified shared by some of the cell lines analyzed (AHSA1, CCNB1, IRAK1), that could represent important HSP90 clients in breast cancer." (PMID 20920318, 2010). "Furthermore, cyclin B1 expression is an independent negative prognostic factor in the breast cancer clinic." (PMID 21172025, 2010). "Unlike CCNB1, CCNA2, and CDK1, currently, the remaining genes (TOP2A, KIF11, and MELK) are not found to be associated with cell cycle; their dysfunctions might still affect the progression and prognosis of breast cancer." (PMID 31428132, 2019). "We first compared the CDK1 and Cyclin B1 protein levels in several common TNBC cell lines (MDA-MB-231, MDA-MB-468, HCC1937, and SUM149PT) and non-TNBC breast cancer cell lines (T47D and MCF-7) with those in 293 cells and normal HDFs." (PMID 32575711, 2020).
hepatocellular carcinoma (94 papers, 2009 to 2025). A malignant tumor that arises from hepatocytes. "Several studies have confirmed that CCNB1 can be used as a diagnostic or prognostic biomarker for rhabdomyosarcoma, hepatocellular carcinoma, and meningioma." (PMID 37592341, 2023). "Several lines of evidence have indicated that CCNB1 is useful as a diagnostic or prognostic biomarker in rhabdomyosarcoma, hepatocellular carcinoma, and meningioma." (PMID 34858418, 2021). "Some researchers have found that CDK1 and cyclin B1 may be potential diagnostic biomarkers for rhabdomyosarcoma and hepatocellular carcinoma." (PMID 33608020, 2021). "CCNB1 has been associated with controlling the cell cycle and DNA replication in hepatocellular carcinoma (HCC), suggesting possible targets for diagnosis and treatment." (PMID 39822992, 2025). "It is intriguing to note that this binding site is lost in the MAD1β spliced form that is prominent in hepatocellular carcinoma cell lines; it is conceivable that the inability to bind cyclin B1, along with the loss of the nuclear localization signal, might contribute to their genomic instability." (PMID 32236513, 2020). "MYC-targeted WDR4 promoted proliferation, metastasis and sorafenib resistance by inducing CCNB1 translation in hepatocellular carcinoma." (PMID 40303931, 2025). "Taken together, these findings suggest that AdipoR1 reduces cyclin B1 expression through the E3 ubiquitin ligase CCNB1IP1 in hepatoma cells." (PMID 39849382, 2025). "For example, CCNB1 overexpression was shown to promote immune infiltration in hepatocellular carcinoma." (PMID 38581717, 2024). "High CCNB1, CCNB2, and CDK1 expression has been associated with inferior prognosis in hepatocellular carcinoma patients." (PMID 38102624, 2023). "In order to confirm the cell cycle arrest of curcumin on hepatocellular carcinoma cells, the cancer cells treated with curcumin were analyzed by flow cytometry and immunostaining of cyclin A1 and cyclin B1." (PMID 37333486, 2023). "CCNB1 promoted tumor cell proliferation and metastasis in hepatocellular carcinoma (HCC) and gastric cancer, and was found to be overexpressed in ACC patients with distant metastasis and was significantly associated with mortality." (PMID 38053725, 2023). "WDR4 interacts with EIF2A to promote the translation of CCNB1, thereby promoting the proliferation, metastasis and sorafenib resistance of hepatocellular carcinoma cells." (PMID 37783676, 2023). "CCNB1 has been reported to be considered other potentially useful genes for targeting hepatocellular carcinoma." (PMID 37592341, 2023). "Costunolide, a eudesmanolide skeleton, induced mitotic arrest, but not progression to the G2 phase, by upregulating the expression of p-Cdk1 (Tyr 15) and cyclin B1 in HA22T/VGH hepatoma cells." (PMID 35056723, 2022). "Four cell cycle-related genes (CDK4, CHEK1, CCNB1, and CDKN2A) were used to establish a risk score to predict the overall survival (OS) of patients with hepatocellular carcinoma (LIHC) in TCGA training set using LASSO Cox regression analysis." (PMID 36403263, 2022). "As CCNB1 is known to be a tumor promoter that influences the immune activity of the hepatocellular carcinoma tumor microenvironment, these results suggest that AE and QR inhibit the proliferation of colon cancer cells by downregulating CCNB1." (PMID 35479514, 2022). "Previous studies showed that CCNB1 was upregulated to promote proliferation of hepatocellular carcinoma via decreased its negative regulators, at least including RNA-binding motif protein 43 (RBM43), miR-199a-3p, or miR-144." (PMID 35078445, 2022).
hepatocellular carcinoma (continued). "The overexpression of RBM43 can inhibit the proliferation of hepatocellular carcinoma cells, and decreased the growth of transplanted tumors in vivo through modulation of cyclin B1 expression." (PMID 34531901, 2021). "The present study revealed that the induction of G2/M phase cell cycle arrest by OPD was correlated with the regulation of Chk1-mediated G2/M checkpoint proteins, including cdc25c/cdc2 and cdc2/cyclin B1 complex pathways, in hepatoma cells." (PMID 31979361, 2020). "Recent in vitro evidence reveals an indispensable role of CCNB1 in the proliferation of human hepatocellular carcinoma cells, which is driven by forkhead box protein M1 (FOXM1)." (PMID 32775402, 2020). "The apoptosis rate of hepatoma cell lines was significantly increased after CCNB1 gene knockdown, suggesting CCNB1 played an important role in the occurrence and development of liver cancer." (PMID 30651720, 2019). "We showed that the mRNA and protein expression levels of CYCLIN B1, a major component driving mitosis entry, are positively correlated in the two studied cohorts, namely, hepatocellular carcinoma (HCC) and prostate adenocarcinoma." (PMID 31354514, 2019). "Meanwhile, further cell function tests confirmed that the proliferation of hepatocellular carcinoma cell lines decreased significantly after CCNB1 knockdown, and the migration and invasion ability and tumorigenic ability decreased significantly." (PMID 30651720, 2019). "In hepatocellular carcinoma, OA can induce G2/M cell cycle arrest, and the G2/M progression of the cell cycle is driven by the maturation promoting factor, a complex of cyclin B1/cdc2." (PMID 29899865, 2018). "In conclusion, costunolide specifically arrests cell cycle at mitosis accompanied by modulation of Chk2/Cdc25c/Cdk1/cyclin B1 signaling and enhancement of radioresponse in human hepatoma HA22T/VGH cells." (PMID 21624128, 2011). "In our study, breast tumors overexpressing TFDP1 had high expression of p16, cyclin E and cyclin B1, as described in hepatocellular carcinoma." (PMID 19995430, 2009). "In addition, the WD repeat‐containing protein 4 (WDR4) promotes G2/M phase transition and hepatocellular carcinoma metastasis by binding eukaryotic initiation translation factor 2A (EIF2A) to Cyclin B1 (CCNB1) mRNA to increase CCNB1 translation." (PMID 39949984, 2025). "Long non-coding RNA (lncRNA) RP11-295G20.2 could bind to miR-6884-3p as a ceRNA to regulate hepatocellular carcinoma progression through Cyclin B1 (CCNB1) pathway." (PMID 38271114, 2024). "HuR targets include invasive and metastatic RNAs (e.g., MMP-9, MTA1, and uPA), angiogenic RNAs (e.g., VEGF-1 and HIF-1), and cell proliferative RNAs (e.g., EGF, cyclin A, cyclin B1, cyclin E, and cyclin D1), through which it can influence hepatocellular carcinoma progression." (PMID 37540723, 2023). "In addition, CCNB1 is also closely related to the proliferation, migration and invasion of hepatoma cells." (PMID 35463358, 2022). "In hepatocellular carcinoma, translation of CCNB1 could promote proliferation, metastasis, and sorafenib resistance, Conversely, methylated CCNB1 may help reduce cancer invasion." (PMID 34745136, 2021). "Another study showed that LINC00312 could downregulate cyclin B1 and induce G2-M cell cycle arrest in hepatocellular carcinoma cells, which downregulated cell proliferation and tumor progression in vivo." (PMID 32340273, 2020).
hepatocellular carcinoma (continued). "In the study, we found that therapy target genes of Jianpi Jiedu decoction were mainly involved in metabolism and apoptosis in hepatocellular carcinoma, and there was a close relationship between the prognosis of hepatocellular carcinoma and the genes of CCNB1, NQO1, NUF2, and CHEK1." (PMID 33424998, 2020). "We also found that OPD effectively suppressed the activity of cyclin B1 and its partner cell division cycle 2 (cdc2) expression, which in turn evokes the prevention of entry into the mitosis (M) phase cell cycle transition in hepatoma cells." (PMID 31979361, 2020). "Overexpression of CCNB1 contributes to the proliferation of colorectal cancer cells, promotes the proliferation, migration, and invasion of bladder cancer, and also leads to poor prognosis of hepatocellular carcinoma." (PMID 32908877, 2020). "CDK1 and CCNB1 have been reported to promote the development of glioblastoma malignancies and are considered potential prognostic biomarkers or therapeutic targets for patients with hepatocellular carcinoma." (PMID 31870357, 2019). "In hepatocellular carcinoma, FoxM1 could regulate cell cycle arrest, and the expression of cyclin B1, p27, and cyclin D1 was all changed in FoxM1 knock out MHCC-97H cells." (PMID 29554906, 2018). "In addition, the overexpression of Cyclin B1 has been identified as a promising poor prognostic marker in patients with hepatocellular cancer, non-small cell lung cancer, and head-neck squamous cell carcinoma." (PMID 25962181, 2015). "For instance, forkhead box protein M1 (FOXM1) activates CCNB1, triggering accelerated hepatocellular carcinoma (HCC) cell proliferation." (PMID 41614789, 2025). "In addition, miR-144 could inhibit human hepatocellular carcinoma by regulating CCNB1, repress the mTOR-VEGF pathway by targeting SGK3 in HCC, and reverse the chemoresistance of HCC cells by suppressing Nrf2." (PMID 33526055, 2021). "Overexpression of miR-144 in hepatocarcinoma cells has similar effects on hepatoma cell proliferation, migration and invasion as CCNB1 knockdown, suggesting that miR-144/CCNB1 regulatory axis may play an important role in the occurrence and development of liver cancer." (PMID 30651720, 2019). "In addition, CCNB1 is an independent predictor of HBV‐related hepatocellular carcinoma recurrence." (PMID 30556321, 2019). "Therefore, cyclin B1 accumulation might be responsible, at least in part, for the ψ-Bufarenogin-triggered G2/M arrest of hepatoma cells." (PMID 25890498, 2015). "Higher frequency of anti-cyclin B1 autoantibody was observed in hepatocellular carcinoma and the basis for autoimmune response to cyclin B1 might include aberrations in cyclin B1 regulation leading to altered protein structure or increased expression which results in stimulation of immune reactions." (PMID 24860838, 2014). "In hepatoma cells, silencing KIF18A reduced the expression of cyclin B1, MMP-9, MMP-7, and Akt-related proteins and inhibited hepatoma cell growth, invasion, and metastasis." (PMID 37965453, 2023). "In hepatocellular carcinoma, WDR4 facilitates the binding of eukaryotic translation initiation factor 2A to cyclin B1 (CCNB1) mRNA, promoting its transcription and enhancing diverse malignant phenotypes." (PMID 37868988, 2023). "In hepatocellular carcinoma, WDR4 interacts with the translation initiation factor EIF2A to promote the translation of CCNB1 and thus promote proliferation, metastasis and sorafenib resistance." (PMID 37783676, 2023). "Caffeine combined with radiation (5 Gy) sensitized tumor cells and tissues by increasing cyclin B1 and caspase-3 cleavage expression, In vitro and in vivo, in LM3 hepatocellular carcinoma cells." (PMID 37240422, 2023).